TBXT (T-box transcription factor T)
Description:
Involved in the transcriptional regulation of genes required for mesoderm formation and differentiation. Binds to a palindromic T site 5'-TTCACACCTAGGTGTGAA-3' DNA sequence and activates gene transcription when bound to such a site.
Synonyms: T; SAVA; TFT
Tractability: Small molecule: a structure with a bound ligand is known.
Gene: Protein-coding gene on chromosome 6 (166,157,656 to 166,168,815, reverse strand). Ensembl gene ENSG00000164458.
Subcellular location: Nucleus
Subcellular location (Human Protein Atlas): Nucleoplasm
Pathways (Reactome):
Developmental Biology: Cardiogenesis; Epithelial-Mesenchymal Transition (EMT) during gastrulation; Formation of axial mesoderm; Formation of definitive endoderm; Formation of paraxial mesoderm; Germ layer formation at gastrulation
Gene Ontology:
Molecular function: DNA-binding transcription factor activity, RNA polymerase II-specific; RNA polymerase II cis-regulatory region sequence-specific DNA binding; RNA polymerase II-specific DNA-binding transcription factor binding; sequence-specific double-stranded DNA binding; DNA-binding transcription factor activity; transcription corepressor activity
Biological process: cardiac muscle cell myoblast differentiation; heart morphogenesis; positive regulation of transcription by RNA polymerase II; anterior/posterior axis specification, embryo; cell fate specification; mesoderm development; mesoderm formation; negative regulation of transcription by RNA polymerase II; primitive streak formation; regulation of transcription by RNA polymerase II; signal transduction; somitogenesis; positive regulation of DNA-templated transcription; regulation of DNA-templated transcription
Cellular component: chromatin; nucleoplasm; nucleus
Genetic constraint (gnomAD): Loss-of-function variants: 20 observed, 43.54 expected, observed/expected ratio (o/e) 0.46, 90% interval 0.32 to 0.67. The upper end of that interval is the gene's LOEUF score, 0.67, which puts it in group 2 of 6, group 1 being the genes least tolerant of losing a copy. Missense variants: 536 observed, 598.63 expected, observed/expected ratio (o/e) 0.9, 90% interval 0.83 to 0.96. Synonymous variants: 213 observed, 246.4 expected, observed/expected ratio (o/e) 0.86, 90% interval 0.77 to 0.97.
Homologues: Orthologues: chimpanzee TBXT (99% identical), macaque TBXT (97% identical), rat Tbxt (92% identical), mouse T (91% identical), guinea pig TBXT (90% identical), dog TBXT (90% identical), pig TBXT (89% identical), rabbit TBXT (74% identical), zebrafish tbxtb (72% identical), tropical clawed frog tbxt.2 (71% identical), Drosophila melanogaster mid (24% identical), Drosophila melanogaster ocm (24% identical), and 9 more. Paralogues in human: TBX19 (54% identical), TBX3 (30% identical), TBX2 (29% identical), TBX5 (29% identical), TBX15 (28% identical), EOMES (28% identical), MGA (28% identical), TBX18 (28% identical), TBX1 (28% identical), TBX4 (28% identical), TBX21 (27% identical), TBR1 (27% identical), and 4 more.
Diseases named in the same sentence as TBXT in open-access papers:
TBXT is named in the same sentence as 205 diseases in open-access papers, as found by Europe PMC text mining. Sharing a sentence is not in itself a finding about the gene and the disease. The quoted sentences say what the papers report.
chordoma (41 papers, 2019 to 2025). Chordomas are rare malignant tumors arising from embryonic remnants of the notochord in axial skeleton. "The TBXT locus is associated with a super enhancer, and degradation of the transcriptional condensate at this locus causes chordoma cells to enter senescence, as does TBXT knockdown, underscoring the dependence of chordomas on TBXT." (PMID 40323130, 2025). "The notochord, BNCTs, and chordomas express the transcription factor TBXT (also known as brachyury), encoded by TBXT." (PMID 40323130, 2025). "Recent studies have identified recurrent mutations in the brachyury gene (TBXT) in chordoma, with up to 70% of tumors showing duplications of this gene." (PMID 39941902, 2025). "Specifically, with immunohistochemistry, chordoma can be diagnosed with positive staining for brachyury, a key transcription factor encoded by the TBXT gene." (PMID 39941902, 2025). "At the molecular level, brachyury, a transcription factor encoded by the TBXT gene, has emerged as a pivotal biomarker and a potential therapeutic target in chordoma." (PMID 40332566, 2025). "As the variant A allele is associated with significantly increased TBXT expression in chordomas, we next asked if the presence of the variant A allele influenced TBXT expression in our cell models." (PMID 40323130, 2025). "Single-nucleotide variants in TBXT have been identified in patients with sporadic chordoma and spinal developmental diseases." (PMID 40901948, 2025). "Amplification of the 6q27 region, which harbors the chordoma susceptibility gene TBXT, was detected in eight patients (16.3%), six of whom exhibited high copy number gains." (PMID 39135136, 2024). "The TBXT is located on the 6q27 region and is associated with susceptibility to chordoma and neural tube defects." (PMID 34837714, 2022). "Our results were in line with those of previous studies showing that TBXT rs2305089 is associated with chordoma development." (PMID 34837714, 2022). "Although TBXT expression is aberrantly changed in other tumors, its expression is a diagnostic hallmark of chordoma." (PMID 34837714, 2022). "So far, genetic characteristics of chordoma has been investigated in respect of the intrinsic tumor characteristics, such as tandem duplication or copy-number gain of TBXT, encoding brachyury." (PMID 36192442, 2022). "Further mutation studies also identified other common variants of TBXT with risk of chordomas, such as rs3816300 in sporadic chordomas and rs1056048 in familial cases." (PMID 36465398, 2022). "TBXT has been reported as a definitive diagnostic biomarker, as chordoma cells need TBXT to survive and maintain their invasive phenotype." (PMID 34837714, 2022). "Among which, the T-box transcription factor (TBXT) Brachyury was first identified, which was mainly expressed in the developing notochord and strongly linked the embryonic structure with chordoma." (PMID 36465398, 2022). "Perhaps unsurprisingly, T (or TBXT), the gene encoding brachyury, appears to be the most selectively essential gene in chordoma." (PMID 36387127, 2022). "The present study investigated the association between TBXT rs2305089 polymorphism and chordoma in an Iranian population." (PMID 34837714, 2022). "Our results were in line with the previous studies showing that TBXT rs2305089 is associated with chordoma development." (PMID 34837714, 2022). "This study demonstrated the association between TBXT rs2305089 and chordoma in an Iranian population using a simple, accurate, and cost‐effective T‐ARMS‐PCR assay." (PMID 34837714, 2022). "Due to the critical relevance of TBXT in the biological mechanisms of chordoma, we investigated germline variants in genes related to TBXT, as well as other genes involved in mesoderm and notochord development." (PMID 34070849, 2021).
chordoma (continued). "The patient and members of her family were involved in extensive genetic studies to identify the genetic abnormality in familial chordoma, which showed TBXT gene duplication on 6q27 and contained a SNP variant rs2305089." (PMID 34465320, 2021). "Chordoma is a rare bone tumor that is typically resistant to chemotherapy and is associated with genetic abnormalities of the T-box transcription factor T (TBXT) gene, which encodes the transcription factor brachyury." (PMID 34465320, 2021). "Beyond being a sensitive chordoma marker, high levels of nuclear brachyury, encoded by the TBXT gene, appear to significantly contribute to tumorigenesis." (PMID 34330313, 2021). "Genes implicated in chordoma formation include the T-brachyury gene (TBXT), which is required for differentiation of the notochord and formation of mesoderm during posterior development." (PMID 34070849, 2021). "The role of TBXT in disease pathogenesis has also been shown to be critical: TBXT expression is considered as a diagnostic marker for chordoma and copy number gains of TBXT have been identified in chordoma tumors." (PMID 34070849, 2021). "TBXT is the only chordoma susceptibility gene identified to date; germline single nucleotide variants and copy number variants in TBXT have been associated with chordoma susceptibility in familial and sporadic chordoma." (PMID 34070849, 2021). "A series of subsequent studies demonstrated duplication of the TBXT gene, a member of the T-box proteins encoding brachyury, that is felt to be a major susceptibility mechanism for the development of chordoma in several families." (PMID 34465320, 2021). "In this study, we investigated rare germline genetic variants in genes involved in TBXT/chordoma-related signaling pathways and other biological processes in chordoma patients from North America and China." (PMID 34070849, 2021). "Similar to other diseases, SEs are associated with genes (TBXT in chordoma) that are critical for disease identity and maintenance." (PMID 32714929, 2020). "Intriguingly, the genomic locus encoding for TBXT has been found to be duplicated or further amplified in familial and sporadic chordoma cases." (PMID 31221659, 2019). "Our initial data on IGFBP3 function in chordoma cells showed that it impairs spheroid growth and that its knockout partially reversed the growth-inhibitory effects of TBXT loss and modulated a subset of the TBXT-regulated proteome." (PMID 40901948, 2025). "IGFBP3 stood out for its extreme up-regulation after TBXT loss in several chordoma cell lines." (PMID 40901948, 2025). "Previous reports examining the association of chordomas with hereditary conditions or germline mutations have focused on the relationship between TBXT variants and familial chordoma and have identified an increased risk associated with the presence of TBXT variants." (PMID 38700789, 2024). "Therefore, increased TBXT expression serves as a hallmark of chordomas and is often used as a diagnostic marker for these specific tumors." (PMID 39051200, 2024). "Chordomas have been linked to the T-box transcription factor T (TBXT) gene located on chromosome 6." (PMID 37111759, 2023). "For instance, TBXT has been found to play an essential role in chordoma pathogenesis, and was associated with SE, where transcriptional cyclin-dependent kinase(CDK)inhibitors could downregulate the expression of brachyury/TBXT." (PMID 35663324, 2022). "Moreover, germline duplication of TBXT is associated with chordoma risk in rare familiar cases, whereas the nonsynonymous SNP rs2305089 can be also found in sporadic chordomas and has prognostic significance in overall survival." (PMID 34330313, 2021). "TBXT is the most relevant susceptibility gene identified in chordoma, with germline TBXT duplication conferring susceptibility to familial chordoma and single-nucleotide polymorphisms (SNPs) in TBXT associated with chordoma risk in both sporadic and familial chordoma." (PMID 34070849, 2021).
chordoma (continued). "TBXT is the only chordoma susceptibility gene identified to date." (PMID 33536423, 2021). "They further demonstrated that TBXT is a SE-associated TF in chordoma." (PMID 32714929, 2020). "Importantly, the transcription factor brachyury (gene name TBXT), a key driver of chordoma, seems linked to this pathway." (PMID 32737414, 2020). "The pathological detection of TBXT protein and the frequently found copy number gains of the TBXT locus, as hallmarks of human chordoma, have been hypothesized to represent tumor-causing insults." (PMID 31221659, 2019). "A quarter of people who develop chordomas are heterozygotes for rs2305089, suggesting that a single variant allele contributes to a predisposition to notochordal tumours and likely explains the modest difference in TBXT expression between genotypes in our study." (PMID 40323130, 2025). "WGBS data revealed hypomethylation of the TBXT promoter (−1800 to +3000 base pairs relative to the transcription start site), compatible with the notion that loss of TBXT promoter DNA methylation may drive increased gene expression in these chordomas." (PMID 34931022, 2021). "A total of 40 Tclin/Tchem DEPs were up-regulated by TBXT inhibition and are thus directly or indirectly suppressed by TBXT in chordoma cells." (PMID 40901948, 2025). "Taking into account the transcripts and proteins deregulated by three independent T-DARPins allowed us to confidently map the TBXT regulome of UM-Chor-1 chordoma cells." (PMID 40901948, 2025). "Together, these results demonstrated that T-DARPins effectively inhibit endogenous TBXT, resulting in reduced proliferation and spheroid growth of chordoma cells and impaired tumor formation in xenografts." (PMID 40901948, 2025). "We developed T-DARPins for two reasons: to generate tools for studying the function of TBXT in chordoma or other TBXT-expressing cancers in a highly specific manner and to provide the basis for molecular mechanism–instructed therapies." (PMID 40901948, 2025). "In the RAB3B‐small‐interfering RNA (siRNA)‐treated chordoma cells, mRNA and protein levels of chordoma stemness markers (TBXT, NANOG, OCT4, and SOX2) were significantly decreased." (PMID 40135815, 2025). "We developed DARPins that effectively and selectively bind TBXT and inhibit its transcriptional function in chordoma cells." (PMID 40901948, 2025). "As expected, owing to the essential role of TBXT in chordoma biology, we observed impaired cell growth by T-DARPin–mediated TBXT inhibition in various experimental models." (PMID 40901948, 2025). "Previous research indicates the involvement of FGFR1 in activating TBXT expression in lung cancer via MAPK signaling, while a super‐enhancer downstream of TBXT is evident in chordoma." (PMID 40099944, 2025). "The effect on the cell cycle and the morphologic changes after TBXT inhibition suggest that chordoma cells undergo senescence—a fate that has been previously reported." (PMID 40901948, 2025). "On the other hand, TBXT expression in the rare cancer, chordoma, is regulated via a super‐enhancer (SE) downstream of the TBXT gene, which binds TBXT protein to maintain its own expression." (PMID 40099944, 2025). "TBXT duplication has been reported in up to 27% of sporadic chordomas, and TBXT is the top selectively essential gene out of ~18,000 genes in chordoma cell lines and patient samples." (PMID 40323130, 2025). "Inhibition of GSK‐3Beta, part of the lysosomal signalling pathway, reduces TBXT expression and sensitises chordomas to chemotherapy." (PMID 40323130, 2025). "These include G177D in the TBXT DBD, which is a risk factor for chordoma and present in up to 94% of patients with chordoma, and R16L and H171R, which are associated with congenital scoliosis and sacral agenesis." (PMID 40901948, 2025). "Designed ankyrin repeat proteins targeting the embryonic transcription factor TBXT provide insights into chordoma biology." (PMID 40901948, 2025).
chordoma (continued). "Because TBXT is an essential driver of mesoderm formation and notochord development, its continued expression and transcriptional activity in chordoma leads to the persistence of an immature cellular phenotype." (PMID 40901948, 2025). "We found that IGFBP3 is glycosylated and secreted in chordoma cells, especially when it is highly expressed after TBXT inhibition." (PMID 40901948, 2025). "The aim of this research was to investigate the pathogenesis of the bone cancer chordoma and the role of the germline rs2305089 SNP in TBXT." (PMID 40323130, 2025). "The experimental knockdown of TBXT in chordoma cell lines results in marked alterations in cellular morphology, including growth arrest and a transition from the characteristic vacuolated cell structure to a spindle-shaped phenotype." (PMID 40332566, 2025). "S2C), this suggested that the T-DARPins altered the binding of TBXT to its superenhancer, leading to suppression of TBXT in chordoma cells by disrupting a previously reported autoregulatory loop." (PMID 40901948, 2025). "The predominant mechanism by which T-DARPins impaired chordoma cell growth was cell cycle disruption, as evidenced by G0-G1 arrest and the most enriched signaling networks in the TBXT-regulated transcriptome and proteome." (PMID 40901948, 2025). "The greater TBXT dependence of chordoma cells in 3D cultures is consistent with TBXT’s function in tissue organization during development." (PMID 40901948, 2025). "Although the pathogenesis of chordoma is not fully understood, TBXT expression in chordomas supports the theory that these tumors arise from remnant NCs that have undergone malignant transformation." (PMID 39051200, 2024). "Albeit usually slow-growing, chordomas can be aggressive mostly depending on their invasive behaviour and according to different histotypes and molecular alterations, including TBXT duplication and SMARCB1 homozygous deletion." (PMID 36983607, 2023). "This study recovered the most significant known dependency gene in chordoma, TBXT, and further revealed a spectrum of additional selectively essential genes in this cancer type." (PMID 37024492, 2023). "CGIs best differentiating chordoma from nucleus pulposus flank the TBXT gene promoter and two DMRs were identified up- and downstream to the promoter (which serves as a genomic map of probes and DMRs)." (PMID 37434245, 2023). "Upregulation of TBXT in chordomas appeared to be related to lower methylation of tumor-specific DMR in gene promoter." (PMID 37434245, 2023). "Lower promoter methylation was related to higher TBXT expression in chordomas that is in line with the results on the regulation of this gene during cell differentiation." (PMID 37434245, 2023). "Pharmacologic inhibition of H3K27-demethylases promotes human chordoma cell death via inducing epigenetic silencing of oncogenic TBXT." (PMID 36520826, 2022). "Compared with other clusters, which were considered putative malignant clusters, putative nonmalignant clusters were checked for lower gene expression levels of chordoma tumor cell markers (TBXT, S100A1, and VIM) according to the published literature 12,18,19." (PMID 36127333, 2022). "In other words, a higher mRNA level of TBXT via the AA genotype was imputed to the expression of downstream targets in chordoma." (PMID 34837714, 2022). "It has been reported that FGF2 and TGF-a involve in chordoma recurrence and FGFR/MEK/ERK/TBXT pathway coordinately regulates chordoma cell growth and survival." (PMID 36520826, 2022). "She had a family history of chordoma and her family underwent extensive genetic study in the past and were found to have a duplication of the TBXT gene." (PMID 34465320, 2021). "COL2A1 was also shown to be down-regulated by TBXT expression in a clival chordoma cell line (UM-Chor1)." (PMID 34070849, 2021). "In summary, we identified candidate driver events (PBRM1+, SETD2+, CDKN2A/B+, TBXT/LYST+) in 33.75% (27 out of 80) of the skull-base chordoma patients we sequenced." (PMID 33536423, 2021).